MYH3 (myosin heavy chain 3)
Diseases named in the same sentence as MYH3 in open-access papers (continued):
Sharing a sentence is not in itself a finding about the gene and the disease.
pregnancy disorder (1 paper, 2021). A disorder that is related to pregnancy. "The involvement of myosins, major contractile proteins, in the pathophysiology of experimental PE may suggest that dysregulation of MYH3 expression is also associated with other pregnancy disorders." (PMID 33923632, 2021).
viral myocarditis (1 paper, 2019). Myocarditis that is caused by an infection with a viral agent. "The viral myocarditis pathway was the only significantly enriched pathway that was distinct to SF; with associated genes falling in the myosin family (Myh2, Myh3, Myh10 and Myh7b)." (PMID 31253821, 2019).
tumor (6 papers, 2019 to 2025). "The tumor displayed a strong activation of genes for mesodermal (Desmin, Myog, Myh1 and Myh3) and endodermal (Afp, Krt20) tissue differentiation." (PMID 33468253, 2021). "Therefore, the available evidence suggests that MYH3 plays a role in tumor initiation and progression, although its specific function remains to be elucidated." (PMID 39684472, 2024). "Moreover, we searched the HPA database for immunohistochemical staining data of TRIP6 and MYH3 in tumor tissues and observed higher protein expression of these genes in analyzed tumor tissues." (PMID 37524774, 2023). "We compared the gene expression levels between normal and tumor tissues of COAD patients from TCGA and found that OXSM was significantly downregulated (p = 5.20 × 10–9), while TRIP6 (p = 5.00 × 10–12), MYH3 (p = 6.70 × 10–3), and MYH4 (p = 6.41 × 10–7) were upregulated in COAD tissues." (PMID 37524774, 2023). "However, further studies are required to elucidate the mechanisms by which MYH3 and MYH15 can promote tumor pathogenesis." (PMID 30967136, 2019). "Interestingly, this cluster also has an elevated expression of MYH3, an embryonic form of myosin heavy chain, several cardiac cytoskeletal genes (ACTC1, TNNT2), and SERPINB9, which has previously been shown to protect tumor cells from granzyme B secreted by cytotoxic T lymphocytes." (PMID 41373578, 2025).
cancer (5 papers, 2019 to 2025). A tumor composed of atypical neoplastic, often pleomorphic cells that invade other tissues. "In TCGA-BRCA database, DCTPP1, SLC27A2, and IFNG were highly expressed in cancer tissues, while MYH3 was expressed at a low level in cancer tissues." (PMID 38753091, 2024). "It has been reported that the downregulation of Myh3 and Eno2 in cancer patients is a good prognostic tool." (PMID 39861068, 2024). "KEGG analysis revealed significant enrichment of DEGs, including TPM1, MYL1, and MYH3, in pathways such as cytoskeleton in muscle cells, alanine aspartate and glutamate metabolism, cGMP-PKG signaling pathway, central carbon metabolism in cancer, and Th17 cell differentiation." (PMID 41007361, 2025).
inflammatory myopathies (4 papers, 2015 to 2025). "Lack of embryonic muscle biopsy material and suitable animal models has hindered study of the pathomechanisms linking mutations in MYH3 to prenatal myopathy." (PMID 26544689, 2015). "In conclusion, this study suggests that developmental p.Thr178Ile MYH3 myopathy is associated with a combined pathomechanism of insufficient dosage of functional embryonic MyHC and production of mutant protein." (PMID 26544689, 2015). "Our data suggest that both mechanisms may have a role in the pathogenesis of DA associated with heterozygous MYH3 mutation, which is probably accompanied by severe myopathy and muscle weakness during foetal development." (PMID 26544689, 2015). "The absence of ACTG1 resulted in muscle weakness and a progressive myopathy in mice; meanwhile, the reduced expression of ACTG1 was closely associated with up-regulated MYH3 induced by RSV." (PMID 35036414, 2021). "Structural muscle genes (ACTA1, TTN) were reduced to levels similar to those in DM, while markers of muscle regeneration (NCAM1, PAX7, MYH3, MYH8) were only mildly increased compared to normal muscle, and lower than in other inflammatory myopathies." (PMID 41441888, 2025).
neuromuscular disease (2 papers, 2015). "Mutations were found in eight previously known neuromuscular disease genes (CHRND, CHNRG, ECEL1, GBE1, MTM1, MYH3, NEB and RYR1) and four novel neuromuscular disease genes (GPR126, KLHL40, KLHL41 and SPEG)." (PMID 26933539, 2015). "Within this cohort, mutations were found in eight previously known neuromuscular disease genes (CHRND, CHNRG, ECEL1, GBE1, MTM1, MYH3, NEB and RYR1) and four novel neuromuscular disease genes were identified and have been published as separate reports (GPR126, KLHL40, KLHL41 and SPEG)." (PMID 26578207, 2015).
lip (1 paper, 2026). "Immunohistochemistry (IHC) for MYH3, IRF6, and GREM1 proteins and chromogenic in situ hybridization (CISH) for IRF6 and GREM1 genes were used to analyze postnatal unilateral right cleft lip tissue (ten patients) and control tissue (six patients)." (PMID 42196143, 2026).
metabolic disease (1 paper, 2025). A congenital disorder (due to inherited enzyme abnormality) or acquired (due to failure of a metabolically important organ) disorder resulting from an abnormal metabolic process. "Although MYH3 has not been directly linked to metabolic diseases, numerous studies have demonstrated its role in modulating TGF‐β signaling and affecting ATPase activity, which may contribute to conditions such as joint contractures and skeletal muscle abnormalities." (PMID 40719081, 2025).
movement disorder (1 paper, 2025). Neurological conditions resulting in abnormal voluntary or involuntary movement, which may impact the speed, fluency, quality and ease of movement. "In conclusion, we have extended the phenotypic spectrum of MYH3 associated disorders by reporting the first neurological features including movement disorders, especially lingual dystonia, in four new patients from the same consanguineous family." (PMID 41180161, 2025). "We report a consanguineous family of four children with two likely pathogenic MYH3 homozygous variants associated with complex movement disorders, especially prominent lingual dystonia, along with skeletal abnormalities." (PMID 41180161, 2025). "All siblings carried two homozygous likely pathogenic variants in MYH3 which seems to be causative for both skeletal abnormalities and movement disorders in this family." (PMID 41180161, 2025). "Up to now, no movement disorders have been described associated MYH3 variants either at the monoallelic or biallelic state." (PMID 41180161, 2025).
muscular disorders (1 paper, 2024). "Unexpectedly, we identified eight patients with pathogenic variants in genes associated with muscular disorders, including MYH3, MYH7, ALPK3, and RYR1." (PMID 38321032, 2024). "Based on current findings, we propose that muscular disorders cause vertebral fusion by inducing mechanical changes in small paraspinal muscles, which is in line with the hypothesis previously raised in a mouse study of the MYH3-related skeletal fusion." (PMID 38321032, 2024).
musculoskeletal diseases (1 paper, 2023). "Mutations in MYH3, the gene encoding MyHC‐embryonic, have been reported to result in a range of musculoskeletal disorders primarily of the distal arthrogryposis (DA) type." (PMID 37492882, 2023). "There are few reports on the muscle pathology of patients with MYH3 mutation‐associated musculoskeletal diseases." (PMID 37492882, 2023). "Thus, YAP signaling is a crucial therapeutic target in MYH3‐associated musculoskeletal diseases such as spondylocarpotarsal synostosis." (PMID 37492882, 2023).
MYH3 also shares sentences with these, for which no sentence is quoted: cardiomyopathies (2 papers); alcoholism (1); atrial septal defect (1); cardiac disease (1); cleft palate (1); clubfoot (1); genetic disease (1); giant axonal neuropathy (1); glioma (1); Hip dysplasia (1); Kyphoscoliosis (1); Miller syndrome (1); muscular dystrophy (1); myocardial infarction (1); orofacial cleft (1); prostate carcinoma (1); ptosis (1); skeletal myopathies (1); Strabismus (1); systemic lupus erythematosus (1); teratoma (1); tongue cancer (1).